PDPN (podoplanin)
Diseases named in the same sentence as PDPN in open-access papers (continued):
Sharing a sentence is not in itself a finding about the gene and the disease.
squamous cell carcinoma (continued). "Thus, podoplanin correlates with higher incidence of lymph node metastasis in early squamous cell carcinoma of the oral cavity and oropharynx." (PMID 26558136, 2015). "Podoplanin is also reported as a potential CSC marker for squamous-cell carcinoma (SCC)." (PMID 24804195, 2014). "The mean surface density of Podoplanin on HEK293T cells, human dermal microvascular endothelial (HMEC-1) cells, and squamous cell carcinoma (FaDu) cells was determined by comparing Podoplanin antibody-stained cells to calibration beads with known antigen binding capacities." (PMID 25368330, 2014). "Aggrus, also known as podoplanin, T1alpha, or gp36, is a type-I transmembrane sialoglycoprotein that is frequently upregulated in many types of tumors, including squamous cell carcinoma, mesothelioma, Kaposi’s sarcoma, testicular germ cell tumor, and brain tumor." (PMID 23991201, 2013). "Although podoplanin-positive TICs in squamous cell carcinomas may use these mechanisms to initiate and sustain tumour growth, they may also proliferate rapidly through the activation of the SHH signalling pathway." (PMID 20196862, 2010). "Podoplanin-positive lymph vessels were commonly located around the tumor or at the tumor boundary, mainly located at adenocarcinoma interstitium, peri-tumor area of squamous cell carcinoma and interstitium of large cell lung cancer." (PMID 19216806, 2009). "The restricted expression of podoplanin at the front of human squamous cell carcinomas prompted the question whether factors of the surrounding tissue could influence podoplanin expression." (PMID 17179989, 2007). "Podoplanin is a mucin-type transmembrane glycoprotein that mediates cell migration and adhesion, and its expression has been reported in squamous cell carcinomas and dysplastic lesions, suggesting that podoplanin may play a role in early oral tumorigenesis and in the malignant transformation." (PMID 36923449, 2023). "In the case of podoplanin, all were significantly associated with a poorer survival outcome, with the exception of multivariate analysis of the OS/DSS outcome group in adenocarcinoma and univariate analysis of the OS/DSS outcome group in squamous cell carcinoma." (PMID 33580106, 2021). "Moreover, our results suggest that PDPN activity may be a therapeutic target for suppressing squamous cell carcinomas in the early stages of metastasis." (PMID 28059107, 2017). "Therefore, podoplanin activity may be a therapeutic target in the treatment of squamous cell carcinomas." (PMID 28059107, 2017). "PDPN primarily interacts with the C-type lectin-like receptor-2 (CLEC-2) and with the standard isoform of hyaluronase receptor CD44s at the surface of squamous cell carcinoma cells by alternative splicing." (PMID 40741180, 2024). "Podoplanin (PDPN) is a membranous sialoglycoprotein and is among the most frequently upregulated genes in squamous cell carcinoma, central nervous system tumors, and germinal neoplasia." (PMID 39451677, 2024). "PDPN expression can also be induced by interferon-γ (IFN-γ), transforming growth factor-β (TGF-β), and tumor necrosis factor-α (TNF-α) in squamous cell carcinoma cell lines." (PMID 40741180, 2024). "PDPN increases tumor cell clonality, EMT, migration, invasion, metastasis and inflammation in tumors including glioma, squamous cell carcinoma, mesothelioma and melanoma and is considered a potential tumor biomarker and therapy target." (PMID 35936713, 2022). "In squamous cell carcinoma (SCC) cells, CD44 and PDPN colocalize on cell surface protrusions, and CD44 is required for PDPN to promote directional and sustained movement of epithelial cells." (PMID 35936713, 2022). "In contrast, PDPN expression, a demonstrated CSC marker in squamous carcinoma cells, while showing similar relationships with different TILs subtypes such as SOX2 and NANOG, was only significantly correlated with stromal and tumoral FOXP3+ cells." (PMID 34201050, 2021).
squamous cell carcinoma (continued). "Podoplanin (PDPN) is a transmembrane sialo-glycoprotein and its overexpression has been detected in many types of tumors, including squamous cell carcinoma, malignant mesothelioma, Kaposi’s sarcoma, testicular seminoma, and brain tumors." (PMID 31208371, 2019). "We previously reported that cell surface marker Podoplanin (PDPN), a mucin-like transmembrane glycoprotein, is a TIC marker of the human squamous cell carcinoma cell line, A43117." (PMID 28059107, 2017). "The purpose of this study is to determine a role of podoplanin in differentiating between HGEIN and early infiltrative squamous cell carcinoma." (PMID 28086225, 2017). "Podoplanin expression was also observed on squamous cell carcinomas but not adenocarcinomas of the lung." (PMID 17179989, 2007). "Recently, investigators have demonstrated that the invasion of squamous cell carcinomas in the area of head and neck does not depend upon cellular dedifferentiation, but on the acquisition of specific tumor cells which express podoplanin at the invasive front of the tumor." (PMID 26558136, 2015). "This is not surprising since podoplanin expression is mainly detected in squamous cell cancers, CNS tumours and germinal neoplasia; in contrast, expression of podoplanin has not been found in the majority of adenocarcinomas, including lung, colon and prostate cancers." (PMID 20196862, 2010).
glioblastoma (51 papers, 2007 to 2026). The most malignant astrocytic tumor (WHO grade IV). "In glioblastoma, podoplanin overexpression strongly associates with intra-tumoral microthrombi and systemic VTE." (PMID 39168144, 2025). "Podoplanin (PDPN) is often found in high amounts in certain tumors like glioblastomas, and its presence has been linked to a poor prognosis." (PMID 39682237, 2024). "MiR-29 inhibits invasion and proliferation of glioblastomas due to targeting podoplanin membrane sialoglycoprotein encoded by PDPN gene were also demonstrated." (PMID 30813461, 2019). "Podoplanin expression in tumor cells is generally associated with poor prognosis, notably in glioblastomas and SCCs of skin, esophagus, and head and neck." (PMID 30736372, 2019). "Immunohistochemical analysis (with or without antigen retrieval), using LpMab‐21 detected membrane‐associated PDPN expression in the human tumor tissues as follows: glioblastoma, oral squamous cell carcinoma (OSCC), and a seminoma." (PMID 28101903, 2017). "Furthermore, a 2.6-fold increased mortality risk was observed in glioblastoma patients with high tumoral podoplanin expression." (PMID 39168144, 2025). "While high tumoral podoplanin expression has been shown to associate with VTE in glioblastoma, probably resulting in the secretion of podoplanin-bearing EVs, a positive correlation has also been described between the risk of glioblastoma-related VTE and both TF-EV levels and activity." (PMID 39168144, 2025). "AsPTENis often inactivated in glioblastoma patients, its ability to regulate podoplanin and TF might explain the increased risk of VTE, especially in combination with oncogenic expression ofEGFR." (PMID 39168144, 2025). "This suggests that high expression of PDPN may be associated with the development, invasion, and immune response of glioblastoma multiforme, indicating its potential relevance to the invasive nature, recurrence, and poor prognosis of tumors." (PMID 38504986, 2024). "However, these parameters are not glioblastoma-specific, and the implementation of TF and/or podoplanin may further increase the prediction value of potential risk stratification tools for VTE in glioblastoma patients." (PMID 39168144, 2025). "PDPN is expressed in some normal adult tissues, such as lymphatic endothelium, and has functionally been implicated in migration, epithelial-to-mesenchymal transition, tumor initiation in squamous cell carcinoma, and inflammation and immune evasion in glioblastoma." (PMID 36059614, 2022). "We and others have previously shown that podoplanin is highly expressed in IDH-wildtype glioblastomas, whereas in IDH-mutant gliomas, its expression is suppressed by promoter methylation." (PMID 40430568, 2025). "Previously, we have developed a cancer-specific mAb targeting podoplanin (PDPN) clone LpMab-2 by immunizing LN229 glioblastoma cells-derived PDPN." (PMID 40688491, 2025). "Mesenchymal glioblastoma has the worst prognosis of all glioblastoma subtypes and exhibits an upregulation in PDPN expression." (PMID 40554484, 2025). "A preclinical study showed the effectiveness of chimeric antigen receptor (CAR)-T cell therapy targeting podoplanin in an orthotopic glioblastoma model." (PMID 40430568, 2025). "We developed a cancer-specific mAb (CasMab) against PDPN, PMab-117 (rat IgM, kappa), by immunizing rats with PDPN-overexpressed glioblastoma cells." (PMID 39594582, 2024). "In the last 5 years, different anti- podoplanin antibody types have been developed for the treatment of cancers, such as glioblastoma and lung cancer." (PMID 38504248, 2024). "The study demonstrated that humLpMab-23-f was able to induce cellular cytotoxicity and exerted high antitumor activity in mouse xenograft models, suggesting its potential as an antibody therapy for PDPN-positive glioblastomas." (PMID 39682237, 2024).
glioblastoma (continued). "PDPN expression in multiple types of cancer (e.g., squamous cell carcinoma, glioblastoma, osteosarcoma, bladder cancer, mesothelioma, and seminoma) triggers platelet aggregation." (PMID 39682237, 2024). "It was observed that the level of PDPN expression varied depending on the grade of the tumors, and all glioblastomas tested positive for PDPN." (PMID 39682237, 2024). "Our group has developed cancer-specific mAbs (CasMabs) against PDPN, which were obtained by immunization of mice with PDPN-overexpressed glioblastoma LN229 cells." (PMID 39594582, 2024). "PDPN is expressed in various cancer cells, such as ovarian cancer, hematologic tumors, glioblastoma, and osteosarcoma." (PMID 38504248, 2024). "In glioblastoma, microRNA-125a is downregulated where it targets podoplanin and inhibits cell migration and invasion." (PMID 36892621, 2023). "We previously established an anti-PDPN mAb (LpMab-23; mouse IgG1, kappa) by immunization with the PDPN ectodomain produced by glioblastoma LN229 cells." (PMID 37894446, 2023). "We successfully applied a PDPN-targeting CasMab to chimeric antigen receptor (CAR)-T therapy in mice preclinical studies of human glioblastoma." (PMID 37894446, 2023). "Podoplanin (PDPN), a type I transmembrane mucin-like glycoprotein that is overexpressed in various cancers, is a potential therapeutic target for the treatment of glioblastoma." (PMID 35991754, 2022). "For the functional examination of this assumption, it is shown that podoplanin on primary human glioblastoma cells induces platelet activation via the specific binding to their C-type lectin receptor type 2 receptors." (PMID 34066760, 2021). "Shiina and colleagues used peripheral blood monocytes transduced with a CAR containing a podoplanin-specific mAb to generate CAR T cells against podoplanin-expressing glioblastomas." (PMID 30736372, 2019). "Thirdly, circulating tumor cells (CTCs) are frequently detected in the blood of glioblastoma patients and, thus, podoplanin-expressing CTCs can detach from the primary tumor and enter the bloodstream." (PMID 30736372, 2019). "We recently produced a single chain Fv fragment (scFv) of an anti-podoplanin mAb (NZ-1) conjugated with immunotoxin, which had an anti-tumor effect in a glioblastoma xenograft model." (PMID 25080943, 2014). "That report revealed that anti-podoplanin mAbs are effective against glioblastoma after crossing the blood-brain barrier." (PMID 25080943, 2014). "Although Aggrus was originally reported as a specific lymphatic endothelial marker protein called podoplanin, it is expressed by various malignant tumors, including squamous cell carcinomas, mesotheliomas, glioblastomas, and osteosarcomas." (PMID 25132683, 2014). "Podoplanin is widely expressed in tumours of the CNS, including ependymal tumours, choroid plexus papillomas, meningeomas, pilocytic astrocytomas and glioblastomas." (PMID 17179989, 2007). "Thus, although a link has been described between VTE and high tumoral podoplanin levels in glioblastoma patients (as compared to patients with low levels), more research is required to determine the role of circulating podoplanin in glioblastoma-related VTE." (PMID 39168144, 2025). "There may also be a role for the epigenetic regulation of PDPN that deserves attention in future studies, for example through isocitrate dehydrogenase (IDH1) mutations in glioblastoma." (PMID 40741180, 2024). "Cultured glioblastoma cells induced platelet aggregation via PDPN." (PMID 40741180, 2024). "Furthermore, they observed markedly higher levels of PDPN mRNA and protein expression in glioblastomas compared with anaplastic astrocytomas, suggesting a potential association between PDPN expression and the malignancy of astrocytic tumors." (PMID 39682237, 2024). "Consequently, CAR-T cell therapy targeting PDPN shows promise as a potential immunotherapy for treating glioblastoma." (PMID 39594582, 2024).
glioblastoma (continued). "PDPN is a key factor for platelet aggregation induced by the glioblastoma cell line, LN319." (PMID 40741180, 2024). "PDPN-positive primary glioblastoma cells induced aggregation of human platelets in vitro, which could be reversed with an anti-PDPN antibody." (PMID 40741180, 2024). "Furthermore, humLpMab-23 reacted with PDPN-positive glioblastoma LN319 and lung squamous cell carcinoma PC-10 cells." (PMID 37894446, 2023). "CLEC-2 and the ligand PDPN might play a significant role in the development and progression of glioblastoma as already hypothesized by other studies." (PMID 38067218, 2023). "According to reports, Podoplanin (PDPN) was a novel candidate gene that might play an essential role in glioblastoma pathogenesis and response to treatment." (PMID 32296458, 2020). "Meanwhile, K-M curves confirmed that these three genes (CCL2, IGFBP2, and PDPN) could be used as independent predictors of survival in patients with glioblastoma." (PMID 32296458, 2020). "In this study, we characterized another clone LpMab‐21, which detects many human cancer cell lines that express PDPN, such as those derived from glioblastomas, lung squamous cell carcinomas, oral squamous cell carcinomas, osteosarcomas, and malignant mesotheliomas." (PMID 28101903, 2017). "High expression of podoplanin was demonstrated in primary brain tumors and contributed to platelet aggregation and hypercoagulability state, suggesting the potential antitumor role of podoplanin inhibitors in glioblastoma." (PMID 28752248, 2017). "Based on the Glioblastoma Multiforme dataset of the PanCancer Atlas (TCGA), we found an inverse correlation betweenCDKN2Aexpression and podoplanin mRNA levels (p = 0.009).123This is the only report on the relation betweenCDKN2A/Balterations and expression levels of podoplanin so far." (PMID 39168144, 2025). "Thus, the exact influence of TF and podoplanin may differ per glioblastoma patient, and a certain degree of cooperation is very likely." (PMID 39168144, 2025). "In conclusion, we found that PDPN may participate to construct the IME in glioblastoma." (PMID 36434176, 2023). "Future studies may include understanding the molecular mechanisms of PDPN’s molecular function in glioblastoma and its interaction with the microenvironment, validating its prognostic role as a clinical biomarker, and further characterizing its potential as a therapeutic target." (PMID 36059614, 2022). "Our work suggests that targeting of PDPN may be a therapeutic option in glioblastoma." (PMID 36059614, 2022). "Therefore, human podoplanin was transfected into LN229 glioblastoma cells (LN229/hPDPN)." (PMID 25080943, 2014). "Furthermore, PDPN has been proposed as a novel biomarker, chemotherapeutic target, and target for chimeric antigen receptor T-cell therapy and may be a potential form of immunotherapy for glioblastoma." (PMID 40554484, 2025). "Nevertheless, since levels of circulating podoplanin have been measured in glioblastoma patients,73and podoplanin-induced platelet activation likely plays a role in thrombogenesis, the use of circulating podoplanin as a prognostic biomarker for glioblastoma-related VTE may be promising." (PMID 39168144, 2025). "In the next paragraphs, two key proteins involved in glioblastoma-related VTE, podoplanin and TF, will be described in more detail." (PMID 39168144, 2025). "The two main procoagulant proteins involved in glioblastoma-related VTE, podoplanin and tissue factor, are described, in addition to the genetic aberrations that can be linked to a hypercoagulable state in glioblastoma." (PMID 39168144, 2025). "Both PDPN and EMP3 were found to be correlated with clinical outcomes in spheroid cultures derived from 20 glioblastomas." (PMID 39941811, 2025). "Glioblastoma multiforme (GBM) is a deadly brain tumor, and podoplanin (PDPN) is a transmembrane glycoprotein found in high amounts in GBM." (PMID 39682237, 2024).
glioblastoma (continued). "This was also found in treatment of glioblastoma cells, U87MG, with monoclonal anti-PDPN antibody, NZ-1, resulting in significant reduction of cell-platelet aggregation." (PMID 40741180, 2024). "humLpMab-23-f exerted antitumor activity against PDPN-overexpressed CHO-K1, endogenous PDPN-positive PC-10 (human lung squamous cell carcinoma), and LN319 (human glioblastoma) xenograft-inoculated mice." (PMID 37894446, 2023). "humLpMab-23 recognized PDPN-overexpressed Chinese hamster ovary (CHO)-K1 (CHO/PDPN), PDPN-positive PC-10 (human lung squamous cell carcinoma), and LN319 (human glioblastoma) cells via flow cytometry." (PMID 37894446, 2023). "Recently, CAR-T cells targeting PDPN were reported, and anti-PDPN CAR-T cells demonstrated strong anti-tumor effects in orthotopic glioblastomas of the mouse brain." (PMID 33238582, 2020). "Aberrantly glycosylated podoplanin including keratan sulfate or aberrant sialylation, which was expressed in LN229 glioblastoma cells, was used as an immunogen." (PMID 25080943, 2014). "In addition to TF, an inverse correlation has been described betweenPTENexpression and podoplanin levels in glioblastoma cell lines in vitro, an in vivo mouse model, and primary glioblastoma samples,117which could very well explain upregulation of podoplanin in glioblastoma." (PMID 39168144, 2025). "Circulating podoplanin is assumed to contribute to glioblastoma-related VTE as well,68, 69, 132but this has not been demonstrated so far." (PMID 39168144, 2025). "Based on single-cell RNA sequencing data, PDPN mRNA varied non-randomly across the individual cells that form human glioblastoma multiforme lesions." (PMID 40741180, 2024). "PDPN-positive human glioblastoma Gli16 cells were able to markedly induce platelet aggregation, whereas not detected by PDPN-negative cells." (PMID 34987523, 2021). "Elevated expression of PDPN is often found at the leading edge of invasive tumor nests, and has been identified as a marker of a cell subpopulation with stem-like characteristics in SCC and glioblastoma cell lines." (PMID 26893367, 2016). "Furthermore, LpMab-3 detected endogenous podoplanin, which is expressed in LN319 (a glioblastoma cell line), a lymphatic endothelial cell (LEC), and NCI-H226 (a malignant mesothelioma cell line)." (PMID 25723283, 2015). "According to our search, we could not find any study under “podoplanin”, “glioblastoma” and “glioblastoma multiforme”." (PMID 39682237, 2024). "They focused on the PDPN molecule that is specifically expressed in the human glioblastoma cell line LN229, which had a different glycosylation pattern compared to the normal cells, and thereafter established CasMab by transplanting LN229 cells expressing PDPN (LN229/hPDPN) into mice." (PMID 32858947, 2020).